RNU1-3 (RNA, U1 small nuclear 3)
Synonyms: HSD4; RNU1G3
Gene: Small nuclear RNA gene on chromosome 1 (16,666,785 to 16,666,948, reverse strand). Ensembl gene ENSG00000207513.
Gene Ontology:
Molecular function: pre-mRNA 5'-splice site binding
Biological process: mRNA 5'-splice site recognition
Cellular component: U1 snRNP
Homologues: Paralogues in human: RNU1-1 (100% identical), RNU1-2 (100% identical), RNU1-27P (100% identical), RNU1-28P (100% identical), RNU1-4 (100% identical), RNVU1-18 (100% identical), RNVU1-29 (100% identical), U1 (100% identical), RNVU1-28 (99% identical), RNVU1-7 (99% identical), RNVU1-31 (99% identical), RNU1-89P (97% identical), and 134 more.